CXCL12 (C-X-C motif chemokine ligand 12)
Diseases named in the same sentence as CXCL12 in open-access papers (continued):
Sharing a sentence is not in itself a finding about the gene and the disease.
tumor (continued). "Furthermore, CXCL12—a chemokine 12 able to bind to its cognate receptor CXCR4 determining the activation of several downstream signaling pathways which regulate tumor progression and metastasis—was found to be significantly downregulated in all the case series." (PMID 35203581, 2022). "Another study reported that blockade of CXCR4/CXCL12 signaling with Plerixafor could also alleviate the desmoplasia and immunosuppression, in turn decompressing tumor vessels and increasing T cell infiltration, eventually enhancing immunotherapy in cold breast tumors." (PMID 34138315, 2021). "Indeed, both HMGB1 and CXCL12 promote tumor cell growth, survival, and invasion." (PMID 33956406, 2021). "However, multiple questions remain unsolved and thus, further exploration of the CXCL12/CXCR4/CXCR7 axes in tumor biology seems to be necessary for a comprehensive understanding of its impact on tumor progression, as well as on CSCs and the maintenance of their niche." (PMID 33530455, 2021). "Significant differences between the two groups were also found for tumor size (6.3 ± 1.5 vs. 11.0 ± 1.1, p = 0.035), Weiss score (4.3 ± 0.6 vs. 6.7 ± 0.4, p = 0.002), and age (38.3 ± 4.6 vs. 53.1 ± 3.8, p = 0.041), with the CXCL12 low-expressing group showing worse parameters." (PMID 34834449, 2021). "Similarly, we found that the expression of GPR15 was positively associated with the levels of tumor-infiltrating immune B cells and DCs and predicted that GPR15 could interact with DC-related CXCL12 to participate in RC progression." (PMID 33833937, 2021). "Furthermore, irradiation induces the local expression of CXCL12 which promotes tumor recurrence." (PMID 34203660, 2021). "It has been suggested that the de novo methylation of the CXCR4 locus may simply be a part of genome-wide process in a distinct subgroup of pancreatic cancers characterized by a profound methylator phenotype and that alternative pathways to CXCR4/CXCL12 may be utilized for tumor progression." (PMID 34901003, 2021). "Therefore, the importance of CXCL12/CXCR4 signaling in HCC tumor cells can be foreseen." (PMID 34386499, 2021). "Significant decreases in the expression of cytokines are associated with tumor-associated macrophages (TAMs), including IL-4, IL-10 CCL-2, CCL-22, and CXCl-12, and suggest that the reduction in macrophages within the treated tumors could be indicative of a decrease in TAMs." (PMID 33956631, 2021). "Our study, demonstrating that CXCL12 secreted by stromal cells activates invasiveness of adjacent cancer cells, suggests that this chemokine triggers mobilization of cells from the primary tumor and provides an alternative explanation to antimetastatic effects of CXCL12 blockade." (PMID 33753872, 2021). "However, the partial tumor inhibitory response induced by tipifarnib is promising and suggests that CXCL12 silencing with tipifarnib may be of particular benefit in this subset of PDAC patients." (PMID 35008248, 2021). "Moreover, CXCL12 results highly downregulated, since it is responsible for chemoattractant activity on T-lymphocytes and monocytes, and is involved in immune surveillance, inflammation response, in surveillance of tumour growth and metastasis." (PMID 33525692, 2021). "However, there are some discrepancies regarding its role in specific tumor types such as PDAC and CRC, which illustrates the complexity of CXCL12 signaling and its receptors in tumor maintenance and progression and highlights the need for further research to resolve these discrepancies." (PMID 33530455, 2021). "High levels of CXCL12 are expressed at common sites of cancer metastasis, such as lung, liver, and bone, and the occurrence of the gradients of this chemokine prompts local invasion and subsequent homing from the primary tumor to the secondary sites of metastasis." (PMID 34834449, 2021).
tumor (continued). "Firstly, macrophage markers IL6, CSF1R, CXCL12 were weak-to-strong positively associated with NEFM expression, which could reveal a potential role of NEFM transcriptional expression in regulating polarization of tumor-associated macrophage (TAM)." (PMID 34001208, 2021). "Additionally, CXCL12 knockdown in ROS induced senescent tumor cells restored T cell attraction." (PMID 33643790, 2021). "However, our results propose that tumor cell‐directed cytotoxicity may only be accomplished upon release of the CD8 TIL from the matrix where TNC binding CXCL12 could be crucial and exploitable for therapy." (PMID 33988305, 2021). "Interestingly, the interaction of MSC with tumor cells modifies their trophic properties through the release of various cytokines such as CXCL1, CXCL2, CXCL12 or IL-6 and metalloproteinases (MMPs) that can degrade the extracellular matrix and promote tumor migration." (PMID 33081024, 2020). "However, CXCL12 expression was found to be markedly related to tumor stage in patients with HNSCC." (PMID 33489879, 2020). "Moreover, CXCL12 has been seen to play an important role in the recruitment and transformation of macrophages into TAMs, which go on to cooperate with and increase the growth of Pit-1-overexpressing tumor cells when co-injected into zebrafish larvae." (PMID 33521055, 2020). "Another group described a model in which stromal and tumor cells influence each other to enhance invasion and angiogenesis: in co-culture conditions, cancer cells stimulate fibroblasts to release higher levels of CXCL12 which, in turn, upregulates PC cell-derived IL-8." (PMID 32012917, 2020). "In addition, endothelial cells surrounding the tumor tissue in LGGs also express CXCL12, what suggests that this chemokine may contribute to the dissemination of tumor cells." (PMID 32456359, 2020). "Furthermore, it was observed that CXCL12 mRNA was related to a more advanced tumor stage." (PMID 33182840, 2020). "Also, besides autocrine CXCL12 expression, peri-tumor immune cells may be inducing CXCL12 expression in the tumor cells they encase, in an attempt to prevent dissemination; this has not been explored before." (PMID 32758242, 2020). "Furthermore, CXCL12 may enhance tumor vascularization also by regulating cellular composition in its microenvironment." (PMID 32148497, 2020). "Additionally, the tumor stroma may deliver inflammatory chemokines affecting tumor development, stroma-derived CXCL12 binds CXCR4 receptor possibly promoting tumor progression by stimulating angiogenesis." (PMID 32499779, 2020). "Additionally, the interaction of CXCL12 with CXCR4 recruits MDSCs, and endothelial cells induce Tregs through TGF-β; both are implicated in the generation of the immunosuppressive tumour microenvironment." (PMID 32466214, 2020). "Moreover, CXCL12/CXCR4 axis plays an important role in tumor growth and metastasis." (PMID 33392074, 2020). "Besides, CXCL12-induced T cell exclusion greatly hindered the anti-tumor effects of anti-PD-L1 monoclonal antibodies, thus AMD3100 synergized with α-PD-L1 could greatly enhance the therapeutic effects on tumor cells." (PMID 33292459, 2020). "Therefore, CXCR4/CXCL12 axis is a significant target for tumor therapy." (PMID 33392074, 2020). "Interestingly, the newly discovered receptor CXCR7 for CXCL12 is highly expressed in many tumor cells as well as tumor-associated blood vessels, although the level of CXCR7 in normal cells is low." (PMID 33129326, 2020). "Therefore, CXCL12/CXCR4 interaction could be considered as an important driving force of MDSC recruitment into the tumor microenvironment." (PMID 30813533, 2019). "However, CXCL12 is also required for the NK cell recruitment, and its weak production in the tumor may participate to the impoverishment of NK cells in the tumor." (PMID 31105699, 2019).
tumor (continued). "In this in vitro and in vivo model-based study, NF-κB/p50 activity regulates the expression of CXCL12 in pancreatic stellate cells, which in turn leads to an immunosuppressive microenvironment by the prevention of a cytotoxic T-cell infiltration into the tumor." (PMID 31561620, 2019). "However, anti-CXCR4 ADC may also target various cell types infiltrating the tumour microenvironment recruited through the CXCL12/CXCR4 pathway and that support tumour growth, such as bone marrow-derived mesenchymal, vascular and myeloid cells." (PMID 30792442, 2019). "Thus, activation of the HSF1 > TGF-beta and CXCL12 mechanism might be predicted to suppress anti-tumor immunity, and may represent a beneficial feature of targeting HSF1 in cancer." (PMID 31514477, 2019). "Therefore, the present study aims to explore the CXCL12 and CXCR4 expression profile in local CRC patients and determine their association with various clinicopathologic factors such as age, tumour differentiation, angiolymphatic and perineural invasion, and their response to chemotherapy." (PMID 29887884, 2018). "Therefore, modulation of the CXCL12/CXCR4 axis in NB tumors could impact multiple aspects of tumor pathogenesis, including immune dysregulation." (PMID 30149659, 2018). "We also tested the possibility that allo-TCXCR4 could outcompete Tregs for limiting CXCL12-dependent niches within the tumor, by adapting the experimental design and cotransferring donor-strain luc+ Tregs at a 1:1 ratio with either TCXCR4 or TControl (both from B6 non-luc+ donors)." (PMID 29485974, 2018). "Interestingly, a recent study using a mouse model of breast cancer showed that TAMs are recruited via CCR2 signaling to primary tumors where they induce CXCR4 expression in response to tumor-derived TGFβ and then migrate toward the blood vessel via CXCL12 to promote intravasation of cancer cells." (PMID 30483271, 2018). "For example, CXCL12/CXCR4 axis is also of high interest for immunotherapeutical approaches due to its crucial role in tumor initiation and progression; therefore, possible future applications might include patient selection and therapy monitoring for targeted therapies." (PMID 30191351, 2018). "We wondered whether circadian oscillations in CXCL12 levels, driven by periodic alterations in cellular secretion rates throughout the body and affecting blood concentrations, would generate gradients in tumor tissue." (PMID 29117251, 2017). "The unsupervised classification of CXCL12 expression values defined 2 groups of samples with the optimal model, which corresponded to a high CXCL12-expressing group (n = 221) that contained 100% of the non-tumor samples and a second group that expressed less CXCL12 (n = 481)." (PMID 28418886, 2017). "CXCL12 secreted from endothelial cells might directly act on tumor cells." (PMID 29100413, 2017). "In addition to TGFβ, CAFs release stromal cell-derived factor 1 (SDF-1/CXCL12), which recruits endothelial progenitor cells to the tumor site to facilitate angiogenesis and directly promote tumor growth via binding to its cognate receptor, CXCR4, expressed by cancer cells." (PMID 28467800, 2017). "Interestingly, p16INK4A-positive senescent cells in CXCR4-expressing tumour cells expressed CXCL12." (PMID 28489070, 2017). "However, they exert antiestrogenic activity in E2-mediated induction of CXCL12 and they maintain the expression of this gene; thus, they might limit the metastatic potential of tumor cells." (PMID 28666461, 2017). "Previous study reported that numerous mast cell-related chemoattractants like CCL5, CXCL12, tumor-derived peptides, transforming growth factor (TGF)-β isoforms, fibroblast growth factor (FGF), and platelet-derived growth factor could drive mast cells migration." (PMID 28938626, 2017). "Finally, the CXCL12/CXCR4 axis was constantly overexpressed in all passages in both tumours." (PMID 28386296, 2017). "However, Roy and colleagues found that CXCL12 serves as a tumor suppressor in PC." (PMID 27542220, 2016).
tumor (continued). "Altogether, these findings suggest that A2BR-induced expression of CXCL12 in stromal cells contributes to its pro-angiogenic effect rather than immune-suppressive effects, establishing a positive cross-talk between fibroblasts and endothelial cells that sustains tumor growth." (PMID 27590504, 2016). "The A2AR agonist CGS21680 did not induce CXCL12 or FGF2 expression in tumor associated fibroblasts." (PMID 27590504, 2016). "Therefore, our results indicated that decreased miR-222 might promote the recruitment of macrophages to the tumor via the CXCL-12/CXCR4 axis." (PMID 26689540, 2015). "This evidence further suggested CXCR4/CXCL12 could potentially promote tumor cell migration." (PMID 26560447, 2015). "Therefore, the CXCL12/CXCR4/ACKR3 pathway could be investigated to target tumor growth, invasion, and proliferation of metastatic cells." (PMID 26441831, 2015). "Therefore, the correlation of CXCR4 and CXCL12 expression levels and tumor invasiveness might be proposed as potential early diagnostic biomarkers." (PMID 26441831, 2015). "Furthermore, forced Pim expression also increases phosphorylation of the CXCR4 chemokine receptor, which may enable the tumor cells to migrate towards tissues such as the lungs that express the CXCL12 chemokine ligand." (PMID 26075720, 2015). "Moreover, according to genotypic and phenotypic evidence of a more close reproduction in vitro of the in vivo tumor characteristics of cultures enriched in CSCs, as compared with established cell lines, recent studies addressed the role of CXCL12 and its receptors in this GBM cell subpopulation." (PMID 24904289, 2014). "Furthermore, this study demonstrates that macrophages are recruited and polarized by signals emitted by MM and BMSCs and recognize the CXCR4/CXCL12 axis as a critical regulator of MM-stroma interactions, shaping the MM tumor niche and contributing to the microenvironment formation." (PMID 25526031, 2014). "Moreover, the role of CXCL12 pathway in tumor resistance, acting both directly, to promote cancer cell and CSC survival and angiogenesis, and indirectly, to recruit stromal cells that through paracrine activity induce recurrence and metastasis, is crucial for cancer therapy." (PMID 24904289, 2014). "CXCL12/CXCR4 axis acts on the tumor microenvironment through the modulation of the expression and secretion of other CKs (i.e., CCL2, CXCL8) and, concomitantly, CXCR4 expression could be influenced by cytokines (TNFα, IFNγ, IL4-6-10) produced by cells in the microenvironment." (PMID 24904289, 2014). "In addition, efficient CXCL12 scavenging by 143B-LacZ-HA-X7 cells shown in vitro may at the primary tumor site also diminish CXCR4-mediated tumor growth promoting activity of CXCL12 in the human 143B OS cell line." (PMID 24040160, 2013). "Furthermore, hypoxia can induce expression of the CXCR4 ligand CXCL12 by the tumor cells." (PMID 24384839, 2013). "However, it is not known whether Akt activation downstream of PTEN loss regulates CXCL12/CXCR4 expression and function in tumor cells." (PMID 23902739, 2013). "Addition of CXCL12 did not increase in vitro wound healing in the Neu-YB cultures, and AMD3100 did not inhibit it, supporting the hypothesis that in this model CXCL12 contributes to a paracrine loop between tumor cells and macrophages within the tumor microenvironment." (PMID 22314082, 2012). "Recent evidence on chemokine stromal derived factor-1 (SDF1, CXCL12) shows that they not only play a key role in neutrophil trafficking but are also involved in the pathways of cell survival, proliferation, and signaling involved in tumor progression, angiogenesis, metastases, and survival." (PMID 22844297, 2012). "Therefore, we hypothesized that similar to normal neural stem cell niches, endothelial cell CXCL12 and tumor cell CXCR4 would play important roles in the biology of the GBM perivascular stem-like cell niche." (PMID 22427929, 2012).
tumor (continued). "We hypothesized that the chemokine CXCL12 and its receptor CXCR4 could mediate direct interactions between GBM cells and tumor-associated endothelial cells and that disruption of this interaction might be the molecular basis for the anti-tumor effects of CXCR4 antagonists." (PMID 22427929, 2012). "Tumor-associated macrophages (TAM) derive mostly from circulating monocytes which are attracted into tumor sites, by locally produced chemotactic factors, such as CCL2, CCL5, CCL7, CCL8, CXCL12, vascular endothelial growth factor (VEGF), and macrophage colony stimulating factor (M-CSF)." (PMID 24212934, 2011). "Finally, we investigated whether the production of CXCL12 within the tumor affected progression-free survival (PFS) and the overall survival (OS) of patients with advanced primary EOC." (PMID 21410972, 2011). "In addition, CXCL12 regulates tumor angiogenesis, a critical step in tumor growth." (PMID 21410972, 2011). "Our results demonstrate CXCL12 derived from tumour cells may also be involved in Treg recruitment." (PMID 21521526, 2011). "However, they may also promote angiogenesis, proliferation and tumor cell invasion, such as the CXCL12 (SDF-1)/CXCR4 axis." (PMID 22180778, 2011). "Expression of membrane receptors such as CXCR4, a Gi protein-coupled receptor for the ligand CXCL12/stromal cell-derived factor 1α (SDF-1α), has been associated with increased proliferation, invasion and migration in GBM as well as in several other tumors and tumor cell lines." (PMID 21489226, 2011). "Thus, CXCL12 can modulate the migration capacity of tumor cells and CXCR7 can enhance tumor growth." (PMID 20049170, 2010). "In addition, high levels of CXCL12 in the tumor microenvironment may disrupt the CXCR4 driven chemotactic response of tumor cells towards CXCL12 expressing tissues such as bone and lung." (PMID 20849618, 2010). "First, CXCR7 could affect CXCL12 induced tumor cell adhesion to ECM." (PMID 20380740, 2010). "IFN-γ was also found to be important for CXCL12-mediated inhibition of 4T1.2 tumor growth which indicates that CD8+ T cells may exert not only direct cytotoxic function against tumor cells, but also indirect effects via IFN-γ-mediated activation of other effector cells." (PMID 20849618, 2010). "In addition, Ssl10 inhibits CXCL12-induced human tumor cell migration." (PMID 20300601, 2010). "This phenomenon indicates that there may be autocrine stimulation by CXCL12 in tumor tissue." (PMID 18983683, 2008). "Furthermore, the correlation between staining intensity and sites of frequent metastasis and CXCL12 staining is further evidence that CD164 may be involved in tumor localization." (PMID 16859559, 2006). "However, we found that SCID mice bearing orthotopic SN12C-VHL-KD tumors demonstrated significantly reduced RCC metastasis to specific organs when CXCL12 was depleted by specific neutralizing antibodies, demonstrating the importance of CXCL12 biology in mediating tumor metastasis." (PMID 17083723, 2006). "In addition, studies have also suggested that CXCL12/CXCR4 may indirectly promote tumor metastases by mediating proliferation of tumor cells and enhancing tumor-associated angiogenesis." (PMID 17083723, 2006). "Inflammatory CAFs (iCAFs) secrete pro-inflammatory cytokines, such as interleukin-6 (IL-6) and C-X-C motif chemokine ligand 12 (CXCL12), which influence immune cell recruitment and promote tumor-promoting inflammation." (PMID 41590379, 2026). "Tumor cells, along with other stromal and immune cells in the TME, secrete chemokines including CCL22, CCL20, and CXCL12, which bind to CCR4, CCR6, and CXCR4 on Tregs and direct their recruitment and activation within the TME." (PMID 41890756, 2026). "For instance, the chemokine CXCL12 (SDF-1), secreted by tumor cells, binds to the CXCR4 receptor to promote invasion and metastasis while recruiting stromal and endothelial cells to support neovascularization." (PMID 41399390, 2026).